TARDBP (TAR DNA binding protein)
Diseases named in the same sentence as TARDBP in open-access papers (continued):
Sharing a sentence is not in itself a finding about the gene and the disease.
frontotemporal dementia (continued). "ALS shares several clinico-pathological features with frontotemporal dementia (FTD), including the accumulation and aggregation of aberrant, intracellular inclusions of TAR DNA-binding protein 43 (TDP-43) that are found in 97% of ALS and 45% of FTD cases." (PMID 40772263, 2025). "Frontotemporal dementia (FTD), another major dementia, is typified by early-onset and by several protein inclusions such as tau, ubiquitin, Fused-in-Sarcoma (FUS) and TAR DNA-binding protein 43 (TDP-43)." (PMID 35159272, 2022). "Non-tau pathology reported in nfaPPA include frontotemporal lobar degeneration-ubiquitin positive inclusions (FTLD-U), Alzheimer’s disease (AD) pathology, frontotemporal lobar-TAR DNA binding protein (FTLD-TDP), and TAR DNA binding protein 43(FTLD-TDP-43)." (PMID 28813486, 2017).
proteinopathy (740 papers, 2008 to 2026). "Inclusions containing TAR-DNA binding protein of 43 kDa (TDP-43) are a hallmark of multiple neurodegenerative diseases collectively referred to as TDP-43 proteinopathies." (PMID 38635657, 2024). "TAR DNA-binding protein 43 (TDP43) deficiency-induced R-loop accumulation has been associated with TDP-43 proteinopathy via DNA replication stress." (PMID 37363169, 2023). "NCT dysfunction has been implicated in FUS and TAR-DNA binding protein 43 kDa (TDP-43) proteinopathies because both of these proteins are normally enriched in the nucleus, although in ALS/FTD spectrum disorders, they are mislocalized in the cytoplasm." (PMID 35784845, 2022). "Further, CVB causes proteinopathy and aggregation of TARDBP, which prevents the biological activity of TARDBP in alternative RNA splicing." (PMID 40396014, 2022). "This indicates that in most patients TDP-43 proteinopathy can manifest in the absence of TARDBP gene mutations, and that other genes are involved in TDP-43 proteinopathy." (PMID 35185458, 2022). "The TDP-43 and its proteinopathy, caused by TARDBP mutations, have been observed both in sporadic ALS and in FALS." (PMID 34362180, 2021). "bvFTD is a clinical phenotype, and, currently there is no in vivo marker that can disentangle the underlying pathology, namely tauopathy or TAR DNA-binding protein 43 (TDP-43) proteinopathy." (PMID 33108404, 2020). "HiPSC-derived astrocytes from patients carrying TARDBP mutations show abnormalities typical of a TDP-43 proteinopathy, including its cytoplasmic mislocalisation." (PMID 27547709, 2016). "Using Drosophila model for proteinopathy associated with TARDBP, it was shown that increasing human wild-type TARDBP expression is sufficient to cause neurotoxicity in vivo." (PMID 23443080, 2012). "One notable pathway involves the proteinopathy associated with TAR DNA-binding protein 43 (TDP-43)." (PMID 40333317, 2025). "Among the 1,495 cases with FTLD where data were available, the underlying proteinopathy was identified as tauopathy in 567 cases (37.93%), TAR DNA-binding protein 43 (TDP-43) proteinopathy in 248 cases (16.59%), and Fused in Sarcoma (FUS) pathology in 8 cases (0.54%)." (PMID 39949536, 2025). "Additionally, limbic-predominant age-related TAR DNA-binding protein 43 (TDP-43) proteinopathy is associated with abundant TMEM-ir material." (PMID 37937069, 2023). "TARDBP mutations display TDP-43 proteinopathy and ALS symptoms identical to sporadic ALS." (PMID 36293362, 2022). "Furthermore, there is a strong, joint association with TAR-DNA-binding-protein (TDP)-43 type C as the underlying proteinopathy, albeit with greater genetic and histopathological heterogeneity in RTLA." (PMID 36698890, 2022). "In this study, we performed mutation analyses of TARDBP, encoding TDP-43, in a large cohort of patients with neurodegenerative diseases characterized by TDP-43 pathology to determine if rare mutations or multiplications in TARDBP are involved in the genetic etiology of TDP-43 proteinopathies." (PMID 18802454, 2008). "In addition to sporadic forms, several mutations in different genes, including the C9orf72 (most frequent), granulin (GRN), valosin-containing protein (VCP), TARDBP, SQSTM1 (sequestome), DCTN1 (dynactin), and OPTN (optineurin) have been reported to be associated with TDP-43 proteinopathy." (PMID 26848654, 2016). "Since rare missense mutations and multiplications have been identified in genes encoding the major constituents of the pathological deposits in several neurodegenerative diseases, we hypothesized that mutations in TARDBP may contribute to the development of TDP-43 proteinopathies." (PMID 18802454, 2008). "Loss of TMEM106B activity and expression enhances TARDBP/TDP-43 burden and is proposed to be a key determinant in the development of TARDBP/TDP-43 proteinopathies, as seen in ALS and FTD." (PMID 41277110, 2026).
proteinopathy (continued). "Other CJD co-pathologies, such as α-synucleinopathies or TAR DNA-binding protein 43 (TDP-43) proteinopathy, were also reported but are comparatively rare." (PMID 41501929, 2026). "Cytoplasmic aggregation of TAR DNA binding protein 43 (TDP-43) in neurons is one of the hallmarks of TDP-43 proteinopathy." (PMID 40234916, 2025). "In terms of classifying diseases by proteins with conformational alterations, TDP-43 (TAR DNA-binding protein) proteinopathies and tauopathies are the most common." (PMID 40149767, 2025). "Neurodegenerative sequelae of TBI commonly include proteinopathies, including TAR DNA-binding protein 43 (TDP-43) proteinopathy." (PMID 39857801, 2025). "TAR DNA-binding protein 43 kDa (TDP-43) proteinopathies are a group of neurodegenerative diseases (NDs) characterized by the abnormal accumulation of the TDP-43 protein in neurons and glial cells." (PMID 40137226, 2025). "Aside from amyloid-beta, multiple proteinopathies, including tau, α-synuclein, TAR-DNA-binding protein 43 (TDP-43), and vasculopathy have been implicated in the pathogenesis of cognitive impairment in Lewy body disease (LBD)." (PMID 40772791, 2025). "Various proteinopathies, such as α-synucleinopathies, TAR DNA binding protein-43 (TDP43) proteinopathies, and others, overlap with typical AD pathologies." (PMID 40074078, 2025). "While these two processes are also involved in many other neurodegenerative diseases, TAR DNA-binding protein 43 (TDP-43) proteinopathy is a pathomechanism specific to ALS and a few other diseases." (PMID 38267984, 2024). "The pathological classification of Perry disease falls under TAR DNA-binding protein 43 (TDP-43) proteinopathies." (PMID 38255218, 2024). "IBM belongs to a group of neurological disorders, the TDP-43 proteinopathies, which pathogenically involve TDP-43 [TAR-DNA-binding protein 43 (transactive response DNA-binding protein of 43 kDa)]." (PMID 38693436, 2024). "The TAR-DNA binding protein 43 (TDP43) has been associated with both sporadic and familial forms of ALS, and is typically observed as cytosolic mislocalization of protein aggregates, termed TDP43 proteinopathy." (PMID 38826483, 2024). "Many NDs are proteinopathies caused by the abnormal aggregation of proteins, such as β-amyloid (Aβ) and tau in AD, α-synuclein in PD, or TAR DNA-binding protein 43 (TDP-43) in ALS." (PMID 37892126, 2023). "Among pathologies found within individual neurodegenerative diseases, proteinopathies of the TAR-DNA binding protein 43 (TDP-43) are a common factor." (PMID 37608352, 2023). "In 2006, prion-like mutations were identified in the C-terminus-encoding regions of the TARDBP gene and deemed causal for autosomal dominant ALS and associated TDP43 proteinopathy." (PMID 37566027, 2023). "Cytoplasmic aggregation of TAR DNA-binding protein 43 (TDP-43) is related to many neurodegenerative diseases referred to as TDP-43 proteinopathies." (PMID 36875699, 2023). "Especially the TDP-43 proteinopathy is one of these hallmarks, as 97% of all ALS cases present histologically with TDP-43-positive inclusions independent of TARDBP mutations." (PMID 39086676, 2023). "FTLD involves one or more proteinopathies: 50% of FTD patients have aggregates of TAR DNA-binding protein 43 (TDP-43, FTLD-TDP) while 45% of FTD patients develops aggregates of the protein tau." (PMID 38332808, 2023). "‘TDP-43 proteinopathy’ refers to human diseases pathologically defined by cellular nuclear-to-cytoplasmic mislocalisation and aggregation of TAR DNA-binding protein-43 (TDP-43), an RNA-binding protein with a crucial role in RNA metabolism and splicing." (PMID 36922834, 2023). "Both hypothalamic nuclei have been proved to be preserved in patients with TDP-43 (TAR DNA-binding protein 43) proteinopathy, suggesting possible differential responses to oxytocin treatments according to the underlying molecular pathologies." (PMID 36232852, 2022).
proteinopathy (continued). "The most common pathological protein aggregates in FTLD include microtubule-associated protein tau, TAR DNA-binding protein 43 (TDP-43), RNA-binding protein fused in sarcoma (FUS), as well as other rare proteinopathies." (PMID 35966773, 2022). "The abnormal distribution, modification, and aggregation of TAR DNA-binding protein 43 (TDP-43) are the pathological hallmarks of a group of neurodegenerative diseases that are collectively known as TDP-43 proteinopathies." (PMID 34759799, 2021). "In other proteinopathies, amyloids and deposits of other proteins, such as TAR DNA-binding protein 43 (TDP-43), α-synuclein (α-syn), and Tau, are found." (PMID 34880726, 2021). "The prime examples of ALS proteinopathy are inclusions formed by mutated superoxide dismutase 1 (SOD1) and ubiquitylated/phosphorylated TAR DNA-binding protein 43 (TDP43) that cannot be cleared by proteasomal and autophagic degradation machinery." (PMID 33343494, 2020). "TAR-DNA binding protein 43 (TDP-43) proteinopathy is a common brain pathology in elderly persons, but much remains to be learned about this high-morbidity condition." (PMID 30567576, 2018). "There is an evolving appreciation of a common brain disease with TAR-DNA binding protein 43 (TDP-43) proteinopathy that mimics Alzheimer’s disease (AD) clinically and affects 10–25% of persons aged 85 or older." (PMID 30567576, 2018). "As model proteins we selected microtubule-associated Tau and TAR-DNA-binding protein 43 (TDP-43), two proteins independently involved in protein misfolding disorders such AD, PD, ALS and FTD23,24." (PMID 29070802, 2017). "For instance, TARDBP mutations, TDP-43 proteinopathy and C9orf72 expansion are common to all three pathologies." (PMID 26300727, 2015). "Like wild-type TDP-43 proteinopathy, mutant TDP-43 in TARDBP-linked ALS patient tissue is characterized by cytoplasmic accumulation as aggregated and insoluble deposits, nuclear clearing in a subset of motor neurons, and C-terminal fragmentation." (PMID 25652699, 2015). "The identification of missense mutations of TARDBP, the gene encoding TDP-43, in familial and sporadic ALS and/or FTLD patients further confirmed the importance of this molecule in the pathogenesis of TDP-43 proteinopathies." (PMID 23840565, 2013). "TAR DNA-binding protein 43 (TDP-43) is a major component within ubiquitin-positive inclusions of a number of neurodegenerative diseases that increasingly are considered as TDP-43 proteinopathies." (PMID 22761693, 2012). "Particularly, neuropathological findings suggest that ALS not only affects the frontotemporal network but rather is part of a wide clinicopathological spectrum of brain disorders known as TAR-DNA binding protein 43 (TDP-43) proteinopathies." (PMID 22720174, 2012). "Characterized by a progressive taupathy and also marked by TAR DNA-binding protein-43 (TDP-43) proteinopathy, CTE has only been found in individuals with a history of repeated brain trauma." (PMID 23984220, 2012). "Detailed neuropathological studies have elicited proteinopathies defined by inclusions of hyperphosphorylated microtubule-associated protein tau, TAR DNA-binding protein TDP-43, fused-in-sarcoma or yet unidentified proteins in affected brain regions." (PMID 22890575, 2012). "Inclusions of TAR DNA binding protein-43 (TDP-43) are the defining histopathological feature of several neurodegenerative diseases collectively referred to as TDP-43 proteinopathies." (PMID 20804554, 2010). "Based on the most important proteins, exemplified by the microtubule-associated tau, alpha-synuclein, amyloid-beta, or TAR-DNA binding protein-43 (TDP-43), diseases are classsified also as tauopathies, synucleinopathies, or TDP-43 proteinopathies." (PMID 19399233, 2009). "Over 50 missense mutations in the TARDBP gene have been identified, yet most drug screening models focus on just a subset of these mutations, which does not adequately capture the varied disease manifestations of TDP-43 proteinopathy." (PMID 38739934, 2024).
proteinopathy (continued). "Results suggest that being a carrier of mutations in MAPT, TARDBP, and TREM2 triggers and accelerates the development of FTD proteinopathies that, eventually, yield a more pronounced effect on the the cognitive, behavioral, and brain tissue impacts associated with FTD." (PMID 36474176, 2022). "Loss of gene expression and splicing regulatory function are now widely accepted features of ALS with TDP-43 proteinopathy, but how the specific complement of TARDBP mRNA targets drives pathogenesis and phenotype remains unclear." (PMID 35946434, 2022). "These disorders may be classified as amyloidosis, tauopathies, α-synucleinopathies, and TAR DNA-binding protein 43 (TDP-43) proteinopathies." (PMID 36231058, 2022). "Furthermore, Kii ALS/PDC is a multiple proteinopathy, presenting as a tauopathy similar to Alzheimer’s disease (AD), α-synucleinopathy similar to Parkinson’s disease (PD), and TAR DNA-binding protein 43 (TDP-43) proteinopathy similar to ALS." (PMID 32422904, 2020). "In addition to tauopathy, CTE is accompanied by other proteinopathies such as amyloidopathy and TAR DNA-binding protein 43 (TDP-43) proteinopathy, the latter of which was originally thought to be a specific marker for ALS that forms ubiquitinated inclusions." (PMID 31551922, 2019). "Cellular and transgenic animal models indicate that both overt proteinopathy, as well as preproteinopathic changes in TDP-43 may be at play in TARDBP-linked disease." (PMID 25652699, 2015). "We synthesize current evidence on the biology of alternative TARDBP splicing, highlight key questions regarding its role in TDP43 proteinopathies such as ALS and FTD, and touch on the larger phenomenon of alternative splicing and its relationship to disease." (PMID 41837283, 2026). "FTLD is a proteinopathy, and the main pathological proteins identified so far are tau, TAR DNA-binding protein 43 (TDP-43), and fused in sarcoma (FUS)." (PMID 37371103, 2023). "Proteinopathies of β-amyloid, tau, α-synuclein, TAR DNA-binding protein 43 (TDP-43), fused in sarcoma (FUS), and prion protein account for the vast majority of human neurodegenerative diseases." (PMID 35813946, 2022). "ALS and the ALS-FTLD spectrum disease are characterized as TDP-43 proteinopathy, where TAR DNA-Binding Protein 43 kDa (TDP-43) links both familial and sporadic forms of ALS." (PMID 36061999, 2022). "Specifically, C9orf72 neuropathology is classified as TDP-43 proteinopathy (Tar DNA binding protein of 43), since most ALS cases and half of FTD cases are characterized by inclusions consisting of the TDP-43 in glia and neurons." (PMID 34362180, 2021). "Wasteosome scores were obtained in various brain regions from 124 post-mortem diagnosed sporadic FTLD patients, including 75 participants with tau (FTLD-tau), 42 with TAR DNA-binding protein 43 (FTLD-TDP), and 7 with Fused in Sarcoma (FTLD-FUS) proteinopathies, along with 29 control subjects." (PMID 38879502, 2024). "Today, both diseases fall under the umbrella term of TDP-43 proteinopathies, in reference to the occurrence of cytoplasmic inclusions of the TAR DNA-binding protein 43 (TDP-43) in glial and neuronal cells: 97% of ALS as well as almost 50% of FTD cases present with such TDP-43-positive inclusions." (PMID 28286471, 2017). "During the course of these proteinopathies, beta-amyloid (Aβ) aggregates in AD, inclusions of hyperphosphorylated microtubule-binding tau in AD and other tauopathies, aggregates of α-synuclein in PD and other synucleinopathies, and inclusions of TAR DNA-binding protein (TDP)-43 in case of ALS occur." (PMID 37759540, 2023). "To date, four major proteinopathies have been identified in FTD patients: Tau, TAR DNA-binding protein 43 (TDP-43), fused in sarcoma (FUS), and ubiquitin positive inclusions, the latter comprising unknown aggregated proteins; with the first two accounting for the vast majority of cases." (PMID 35281504, 2022).
proteinopathy (continued). "Other familial ALS mutation phenotypes, such as valosin-containing protein (VCP), TAR DNA-binding protein 43 (TDP-43), and superoxide dismutase (SOD1), have been recapitulated in iPSCs showing characteristic proteinopathies, and endoplasmic reticulum (ER) and oxidative stress." (PMID 29479303, 2018). "TAR DNA-binding protein (TDP-43) has been identified as a major component of cytoplasmic inclusions in sporadic and most familial ALS cases, as well as in frontotemporal lobar dementia (FTLD) with ubiquitinated inclusions, coupling these two diseases as TDP-43 proteinopathies." (PMID 26444430, 2015). "Nonetheless, our data evidence positive cardiovascular‐related associations across genotypes reflecting both tau and TAR DNA‐binding protein 43 (TDP‐43) proteinopathies, suggesting benefits of systemic cardiovascular health in FTLD may not be specific to one type of proteinopathy." (PMID 39240048, 2024).